EVC2 (EvC ciliary complex subunit 2)
Description:
Component of the EvC complex that positively regulates ciliary Hedgehog (Hh) signaling. Plays a critical role in bone formation and skeletal development. May be involved in early embryonic morphogenesis.
Synonyms: LBN; WAD
Tractability: Antibody: UniProt places it where antibodies can reach, with medium confidence; UniProt predicts a signal peptide or a membrane-spanning region; its Gene Ontology location is reachable by antibodies, with medium confidence.
Gene: Protein-coding gene on chromosome 4 (5,542,772 to 5,709,548, reverse strand). Ensembl gene ENSG00000173040.
Subcellular location: Cell membrane; Cytoplasm, cytoskeleton, cilium basal body; Cell projection, cilium; Cell projection, cilium membrane; Nucleus
Subcellular location (Human Protein Atlas): Cytokinetic bridge; Microtubules; Plasma membrane; Primary cilium; Basal body; Cytosol; Nucleoplasm; Primary cilium tip
Pathways (Reactome):
Signal Transduction: Activation of SMO; Hedgehog 'on' state
Gene Ontology:
Biological process: smoothened signaling pathway
Cellular component: nucleus; ciliary membrane; cilium; plasma membrane; plasma membrane protein complex
Genetic constraint (gnomAD): Loss-of-function variants: 146 observed, 153.44 expected, observed/expected ratio (o/e) 0.95, 90% interval 0.83 to 1.09. The synonymous counts are far from expectation, so gnomAD's model fits this gene poorly and the ratio says little. Missense variants: 1,854 observed, 1,655.1 expected, observed/expected ratio (o/e) 1.12, 90% interval 1.08 to 1.16. Synonymous variants: 776 observed, 660.3 expected, observed/expected ratio (o/e) 1.18, 90% interval 1.11 to 1.25.
Gene-disease validity (ClinGen):
ClinGen rates the evidence that EVC2 causes each of these diseases.
acrofacial dysostosis, Weyers type (autosomal dominant): Definitive. Acrofacialdysostosis, Weyers type (WAD) is a rare ectodermal dysplasia syndrome with bone abnormalities characterized by onychodystrophy; anomalies of the lower jaw, oral vestibule and dentition; post-axialpolydactyly; moderately restricted growth with short limbs; and normal intelligence.
Ellis-van Creveld syndrome (autosomal recessive): Definitive. Ellis-van Creveld syndrome (EVC) is a skeletal and ectoderlam dysplasia characterized by a tetrad of short stature, postaxial polydactyly, ectodermal dysplasia, and congenital heart defects.
Homologues: Orthologues: chimpanzee EVC2 (98% identical), macaque EVC2 (95% identical), dog EVC2 (77% identical), pig EVC2 (75% identical), guinea pig EVC2 (67% identical), mouse Evc2 (67% identical), rat Evc2 (65% identical), rabbit EVC2 (63% identical), tropical clawed frog evc2 (36% identical). Paralogues in human: EVC (12% identical).
Diseases named in the same sentence as EVC2 in open-access papers:
EVC2 is named in the same sentence as 44 diseases in open-access papers, as found by Europe PMC text mining. Sharing a sentence is not in itself a finding about the gene and the disease. The quoted sentences say what the papers report.
Ellis-van Creveld syndrome (19 papers, 2010 to 2025). "The association between EVC2 and congenital tooth agenesis has been increasingly recognized, in both Ellis-van Creveld syndrome and NSTA." (PMID 41300740, 2025). "Mutations in EVC2 can lead to Ellis-van Creveld syndrome or Weyers acrofacial dysostosis, both of which are commonly associated with dental developmental defects." (PMID 41300740, 2025). "EVC2, encoding EvC ciliary complex subunit 2, is associated with Ellis-van Creveld syndrome (MIM: 225500)." (PMID 38608674, 2024). "Mutations in EVC2 cause congenital heart disease, shortened limbs, short stature, and dental abnormalities known as Ellis-van Creveld syndrome." (PMID 34770175, 2021). "Mutations in the EVC2 gene have been related to Ellis-van Creveld syndrome and Weyers acrofacial dysostosis." (PMID 29259192, 2017). "EVC2 is a protein coding gene, and related to bone formation and skeletal development, and is well known as causal for Ellis-van Creveld syndrome, which has clinical features including limb and facial abnormalities, and heart defects." (PMID 27733454, 2016). "EVC2 plays a critical role in bone formation and skeletal development and mutations in EVC2 are associated with Ellis van Creveld syndrome in which 50-60% of congenital heart defects occur." (PMID 24479926, 2014). "The gene encoding Evc2 is in close proximity in divergent orientation to Evc and mutations in both human genes lead to the chondrodysplasia Ellis-van Creveld syndrome." (PMID 21356043, 2011). "Hedgehog signaling modulates patterning and morphogenesis of most organs in mammalian embryo, and mutations in EVC or EVC2 disrupt the hedgehog signaling in bone development, with a high proportion of Ellis-van Creveld syndrome patients presenting mutations in EVC2." (PMID 30791866, 2019). "Among the positional candidate genes, EVC and EVC2, near SNPs associated with HD on CFA03, cause Ellis–van Creveld syndrome (EVC, MIM 225500), a rare autosomal recessive chondrodysplasia also called chondroectodermal or mesoectodermal dysplasia." (PMID 20949002, 2010).
ciliopathy (6 papers, 2016 to 2023). A genetic disorder of the cellular cilia or the cilia anchoring structures, the basal bodies, or of ciliary function. "EVC syndrome is categorized as a ciliopathy due to the ciliary localization of proteins encoded by the causative genes of EVC syndrome, EVC and EVC2/LIMBIN." (PMID 38606060, 2022). "EvC syndrome is also categorized as a ciliopathy because of ciliary localization of proteins encoded by the two causative genes, EVC and EVC2 (aka LIMBIN)." (PMID 28027321, 2016). "Interestingly, a duplication of aa 1293-1300 in human EVC2 was found in association with Meckel-Gruber syndrome (MKS), a severe ciliopathy." (PMID 37576597, 2023). "In addition to this, 661W cells express several syndromic ciliopathy disease genes which are not expressed at all in hTERT-RPE1 cells, including B9d1, B9d2, Evc2, Pkd1, and Tmem138." (PMID 31024622, 2019).
dwarfism (4 papers, 2007 to 2025). "Interestingly, LIMBIN, originally identified as the causative gene for chondrodysplastic dwarfism in Japanese Brown cattle, was later discovered as the cattle orthologue of EVC2." (PMID 28027321, 2016). "Inactivation mutations in Evc or Evc2 within the perichondrium result in markedly elevated FGF signaling, leading to severe dwarfism characteristic of Evc syndrome." (PMID 40671824, 2025). "Our findings explain differences between proposed functions of EVC/EVC2 based on biochemical approaches and symptoms found in the EvC patients, and thus provide insight for better options to treat dwarfism found in EvC patients." (PMID 28027321, 2016). "We have additionally demonstrated that elevation of FGF signaling in growth plates due to loss of Evc2 function in the perichondrium plays a critical role in the pathogenesis of dwarfism in Evc2 mutants." (PMID 28027321, 2016). "We conclude that both reduced Hedgehog signaling and elevated FGF signaling play a critical role in the pathogenesis of the unique form of dwarfism that characterizes Evc2 mutants." (PMID 28027321, 2016). "Mutations in the LIMBIN gene, a bovine orthologue of EVC2, are associated with bovine chondrodysplastic dwarfism." (PMID 17547743, 2007). "To further demonstrate that Evc2 loss of function in the perichondrium is critically involved in the elevation of FGF signaling and pathogenesis of dwarfism, we used the Dermo1(Twist2)Cre allele that demonstrates recombination in both chondrocytes and the perichondrium." (PMID 28027321, 2016). "Therefore, both elevated FGF signaling and a compromised Hedgehog-PTHrP feedback loop likely contribute critically to the pathogenesis of dwarfism in Evc2 mutants." (PMID 28027321, 2016). "ATC-dependent Evc2 conditional mutants allowed us to exclude the impact of FGF signaling and thereby to evaluate how a compromised Hedgehog-PTHrP feedback loop results in dwarfism." (PMID 28027321, 2016).
chondrodysplasia (3 papers, 2011 to 2018). "Our previous studies interestingly identified the bovine ortholog EVC2/LIMBIN as a causative gene for chondrodysplasia in Japanese brown cattle." (PMID 30410447, 2018). "All these genes are highly expressed in cartilage and mutations in these genes can cause chondrodysplasia (EVC, EVC2), Marfan syndrome (MFAP1) or restless legs syndrome (PTPRD)." (PMID 24802516, 2014).
acrofacial dysostosis (2 papers, 2020 to 2025). "Mutations in either EVC2 or EVC are known to cause autosomal recessive Ellis-van Creveld syndrome or the autosomal dominant Weyers acrofacial dysostosis." (PMID 41300740, 2025). "According to further genotype–phenotype analysis, we found that heterozygous mutations of EVC2 gene are responsible for Weyers acrofacial dysostosis (OMIM 193530), which were mainly characterized by mild short stature, postaxial polydactyly, and so on." (PMID 32543076, 2020).
breast carcinoma (2 papers, 2022 to 2024). "EVC2 positively modulated Hedgehog (Hh) signaling pathway by forming complex with SMO protein and transduced Hh signaling in recipient breast cancer cells." (PMID 35148692, 2022).
microtia (2 papers, 2014 to 2015). "Our results warrant further investigation of the EVC2 mutations for the microtia phenotype in the pedigree." (PMID 26035869, 2015). "Interestingly, a susceptibility locus for isolated bilateral microtia in a five-generation Chinese pedigree has been recently mapped to a 10-Mb region encompassing the EVC2 gene." (PMID 26035869, 2015). "Based on the knowledge that microtia is one of the facial deformities with cartilage abnormity, we suggest detailed investigations on the EVC, EVC2, SLC2A9, NKX3-2 and HMX1 genes for this isolated microtia pedigree." (PMID 24983964, 2014).
acrofacial dysostosis, Weyers type (1 paper, 2011). "Defects in LBN (EVC2) are a cause of acrofacial dysostosis Weyers type (WAD, also known as Curry-Hall syndrome)." (PMID 21533267, 2011).
atrial septal defect (1 paper, 2025). Interauricular communication is a congenital malformation characterized by a communication between the atrial chambers of the heart. "Variants in genes associated with atrial septal defects and ventricular septal defects (e.g., DOCK6, EOGT, EP300, EVC, EVC2, and SEMA3C) have also been identified in patients." (PMID 41153298, 2025).
breast tumors (1 paper, 2024). "A study with breast tumors found significant mutations in the EVC2 gene, but in the metastases and not in primary tumors, thus suggesting targets for metastasis inhibition." (PMID 39057100, 2024).
deafness (1 paper, 2019). An inherited or acquired condition characterized by the complete loss of the ability to hear from one or both ears. "The use of inherited disease genes sequencing panel identified the causative and novel variants in deafness related genes (GJB2, MYO7A, CDH23, TH and EVC2) in deaf brothers." (PMID 30881389, 2019). "It is concluded that in addition to novel mutations in MYO7A, TH and EVC2, the CDH23 and GJB2 can also be responsible for deafness in the family with consanguineous marriages." (PMID 30881389, 2019).
ectodermal dysplasia. (1 paper, 2025). "EVC2 mutations are involved in tooth agenesis and ectodermal dysplasia." (PMID 40687612, 2025).
enamel hypoplasia (1 paper, 2025). "EVC2 loss-of-function results in delayed ameloblast differentiation by disrupting HH signaling in the dental epithelium, clarifying the pathogenesis of enamel hypoplasia in patients with EVCS." (PMID 40726901, 2025).
Mitral regurgitation (1 paper, 2025). An abnormality of the mitral valve characterized by insufficiency or incompetence of the mitral valve resulting in retrograde leaking of blood through the mitral valve upon ventricular contraction. "However, the individual carrying a compound heterozygosity genotype, p.Arg663Pro and c.1316-7A>G, only exhibited mild mitral regurgitation, indicating that some hypomorphic mutations could still produce a sufficient amount of functional EVC2 protein." (PMID 40726901, 2025).
tooth agenesis (1 paper, 2025). A tooth disease characterized by failure to develop one or more missing teeth. "While EVC2 has emerged as a promising candidate gene for congenital tooth agenesis, the exact pathogenic mechanisms remain elusive." (PMID 41300740, 2025).
skeletal dysplasia (3 papers, 2010 to 2025). Any Mendelian diseases that affects growth and development of the skeleton. "As the mutations in these genes always cause skeletal dysplasia, we suggest that some novel mutations in EVC2 and EVC may be relevant to the form of mandibular prognathism." (PMID 20844756, 2010). "This case represents the first identification of the EVC2 p.E87G and p.S217C, and the isolated CHD without visible skeletal dysplasia is an important feature of our case." (PMID 40726901, 2025).
cancer (2 papers, 2021 to 2025). A tumor composed of atypical neoplastic, often pleomorphic cells that invade other tissues. "Another notable observation includes EVC2’s involvement in the cancer-implicated Hedgehog signalling pathway, though its specific role in PCa requires further investigation." (PMID 41057544, 2025). "The genes preferentially mutated in metastases were MYLK, PEAK1, SLC2A4RG, EVC2, XIRP2, PALB2, and ESR1 (five of which are not significantly mutated in any type of human primary cancer)." (PMID 34771579, 2021).
EVC2 also shares sentences with these, for which no sentence is quoted: cleft palate (2 papers); congenital heart disease (2); Marfan syndrome (2); tumor (2); achondroplasia (1); basal cell nevus syndrome (1); blepharocheilodontic syndrome (1); Cornelia de Lange syndrome 4 (1); Floating-Harbor syndrome (1); gastric tumors (1); Hip dysplasia (1); ichthyosis (1); incontinentia pigmenti (1); Joubert syndrome (1); lung carcinoma (1); Meckel-Gruber syndrome (1); microdeletion syndrome (1); Microdontia (1); Oligodontia (1); Opitz G/BBB syndrome (1); orofaciodigital syndrome (1); polydactyly (1); restless legs syndrome (1); short rib thoracic dysplasia (1); ventricular septal defect (1); Williams-Beuren syndrome (1); Wolf-Hirschhorn syndrome (1).